STAT3 (signal transducer and activator of transcription 3)
Diseases named in the same sentence as STAT3 in open-access papers (continued):
Sharing a sentence is not in itself a finding about the gene and the disease.
psoriasis (continued). "STAT3 has also been implicated in inducing the expression of Keratin 17, a proposed autoantigen in psoriasis, downstream of IL-22, IL-17, and other cytokines." (PMID 29316631, 2018). "Strikingly, IL-23, its receptor, and its downstream signaling molecule STAT3 are all linked to the genetic susceptibility for developing psoriasis." (PMID 27158469, 2016). "Stat3C transgenic mice, in which keratinocytes express constitutively active Stat3 (PY-Stat3), developed psoriasis-like skin lesions, suggesting that Stat3 activation caused disease pathogenesis." (PMID 26893174, 2016). "Psoriasis is associated with activation of an IL-22 and IL-6/STAT3 pathway, which contributes to keratinocyte hyperproliferation and failure to exit the cell cycle with the inability to fully mature into corneocytes." (PMID 27537526, 2016). "It has been shown that STAT3 is involved in the upregulation of keratin 17, a hallmark of psoriasis, in keratinocytes following IL-17A stimulation." (PMID 27711196, 2016). "We also observed enhanced STAT3 activation in skin tissue of transgenics and upregulated expression of psoriasis-associated chemokines/cytokines." (PMID 27698489, 2016). "In a three-dimensional human epidermis model, IL-22 and IL-20 cause psoriasis-like morphologic changes associated with the inhibition of keratinocyte terminal differentiation and STAT3 upregulation." (PMID 23365685, 2013). "Conversally, PPARγ inhibits STAT3 which, when overexpressed, induces Wnt5a and causes a psoriasis-like phenotype in vivo." (PMID 19399181, 2009). "In addition to other models, we have added a defined psoriasis predisposing factor to the model, the overexpression of STAT3." (PMID 40678130, 2025). "For example, in the imiquimod (IMQ)-induced psoriasis model, enhanced features of psoriatic inflammation are associated not only with increased expression of STAT3, NF-kB, IFN-γ and TNF-α in CD4+ T cells but also activation of lymphocyte-specific protein tyrosine kinase (Lck)." (PMID 40868162, 2025). "By inhibiting STAT3 phosphorylation, piperine effectively ameliorates psoriatic skin lesions and reduces inflammatory cell infiltration by decreasing the expression of cytokine and chemokines associated with psoriasis." (PMID 40161116, 2025). "In addition to S100A7 and p-STAT3, the expression profiles of further psoriasis associated secreted immune mediators of the wild type and TLR2 or TLR3 KO epidermis models after stimulation with Pam2CSK4 or poly(I:C) were investigated with a multiplex assay." (PMID 40995100, 2025). "Uncontrolled STAT3 activation is strongly implicated in the development of psoriasis." (PMID 39833165, 2025). "STAT3 plays a pivotal role in inflammatory cytokine secretion by Th17 cells, keratinocytes, and γδ T cells, and its abnormal activation is strongly associated with the development of psoriasis." (PMID 40405066, 2025). "STAT3 functions as a central regulator in the inflammatory responses associated with psoriasis." (PMID 40405066, 2025). "Thus, we showed by immunohistochemical staining and quantification of the metabolic activity that the epidermis models established from STAT3 overexpressing keratinocytes responded with a higher sensitivity to psoriasis associated cytokines." (PMID 40678130, 2025). "STAT3, in particular, has been implicated in several autoimmune diseases, including psoriasis." (PMID 37822943, 2023). "Additionally, in the skin of NRF2-deficient psoriasis-like mice, the STAT3 and NF-κB pathways were activated, and K16 expression increased." (PMID 38007430, 2023). "Genome-wide association studies (GWAS) have established a relationship between the JAK-STAT pathway and IMIDs, For example, JAK2, Tyk2, STAT1, STAT3, STAT4, and IBD; TyK2, TAT1, SLE; TyK2, STAT4, RA; and TyK2, STAT3, and psoriasis are closely linked to the JAK-STAT pathway." (PMID 37351513, 2023). "In the case of STAT3, the rs744166 SNP was linked to increased risk of psoriasis." (PMID 37569685, 2023).
psoriasis (continued). "Stat3 has been identified as a genetic susceptibility locus in human psoriasis." (PMID 37226685, 2023). "Also, Lrig1 KO mice show psoriasis-like epidermal hyperplasia with the over-proliferative ability of keratinocytes, and further loss of Lrig1 causes chronic inflammation through the STAT3-dependent pathway." (PMID 37666819, 2023). "STAT3 plays a critical role in differentiating both Th17 cells and Tregs from naïve CD4+ precursors, and the mechanism by which miR-125a-5p regulates the immune response of CD4+ T cells in psoriasis pathogenesis may also be associated with STAT3." (PMID 37773129, 2023). "In this study, there was also a marked decrease in psoriasis-associated STAT3 activation in epidermal cells of IMQ-induced C57BJ6 mice after fisetin treatment, suggesting that fisetin disrupts the positive immune to skin trafficking feedback that drives psoriasiform dermatitis." (PMID 36741386, 2022). "In addition, the psoriasis cytokines caused an increased phosphorylation and nuclear translocation of STAT3." (PMID 34641358, 2021). "The risk of malignancy in patients with psoriasis is thought to be slightly increased compared to that in the normal population; thus, we speculated that STAT3 activation in psoriasis patients is related to malignancy risk." (PMID 34679602, 2021). "For instance, single-nucleotide polymorphisms (rs734232) affecting the consensus-binding site for RUNX1, or Runx1 itself, are associated with susceptibility to rheumatoid arthritis and psoriasis, while Stat3 gene was identified as risk locus for Crohn's disease and MS." (PMID 32226427, 2020). "Polymorphisms of genes encoding Th17-associated factors, such as IL-23, IL-23 receptor and relevant signaling molecules including suppressor of cytokine signaling (SOCS) 1 and signal transducers and activators of transcription 3 (STAT3) are associated with psoriasis." (PMID 33171607, 2020). "STAT3 participates in signaling downstream of multiple cytokines implicated in psoriasis, such as IL-6, IL-10, IL-20, IL-22, and IL-23, and may have a role in mediating the innate immune response in psoriatic epidermis." (PMID 32752186, 2020). "STAT3 gene variations are also associated with increased predisposition to psoriasis." (PMID 32886659, 2020). "Unrestrained activation of STAT3 is linked to pathologies such as neoplastic diseases and autoimmune/autoinflammatory conditions, including rheumatoid arthritis, uveitis, Multiple Sclerosis, myocarditis, and, finally, psoriasis." (PMID 29316631, 2018). "Additionally, a GWAS study found that psoriasis was associated with mutations in STAT3 (signal transduction and transcriptional activator 3), which is a key molecule in signaling cascades via several cytokines, including IL-6, IL-10, IL-22, and IL-23." (PMID 29292715, 2017). "Moreover, both genotypes showed comparable STAT3 activation and expression levels of psoriasis-associated chemokine/cytokines." (PMID 27698489, 2016). "HO-1 was hypothesized as a feasible therapeutic target of psoriasis because HO-1 counteracted Stat3-linked aberrant differentiation and proliferation in keratinocytes." (PMID 26893174, 2016). "STAT3 activation has a key role in the psoriasis-associated IL-23 signaling cascade." (PMID 25126586, 2014). "PPARβ/δ activation evidently causes psoriasis-like disease not solely through STAT3 activation since (i) the phenotype is not completely reversed by inhibition of STAT3 and (ii) overexpression of STAT3 alone causes a less widespread psoriasis-like phenotype with a much longer latency." (PMID 20300524, 2010). "Furthermore, our results show that the genes mediating the development of IBD in psoriasis may be associated with the following genes CSF2RA/SOCS1/PTPN2/STAT3/IL21R, which has implications for the exploration of co-morbid targets in PsO combined with IBD." (PMID 38803495, 2024).
psoriasis (continued). "Shikonin is a 288-kDa liposoluble naphthoquinone derived from Lithospermum erythrorhizon, which could suppress IL-17-induced production of cytokines associated with psoriasis by inhibiting the JAK/STAT3 signaling pathway and suppression of CEBPD downregulation." (PMID 35485255, 2022). "Therefore, we designed this study to determine whether patients with psoriasis are susceptible to STAT3 activation in tumors." (PMID 34679602, 2021). "Patients with psoriasis may have a genetic background that predisposes them to STAT3 activation." (PMID 34679602, 2021). "Therefore, BBR could inhibit STAT3 in both immunocytes and keratinocytes that are implicated in psoriasis development." (PMID 30894513, 2019). "Furthermore, psoriasis-related mutations in STAT3 may reduce the threshold for the IL-23 signal required to induce Th17 polarization." (PMID 29292715, 2017). "For chronic pruritus, LCN2 modulates the excitability of pruritus-related neurons via pathways such as the IL-6/STAT3 axis, and participates in the pathological processes of pruritus in allergic contact dermatitis, xerosis, atopic dermatitis, and psoriasis." (PMID 42088581, 2026). "Studies have found that keratinocytes overexpressing STAT3 in model mice lead to the spontaneous development of psoriasis-like lesions, and that their cytokine distribution is similar to that of human psoriasis plaques." (PMID 40427630, 2025). "The objective of this study was to examine the therapeutic efficacy of EGT in a psoriasis model and to elucidate the underlying mechanisms of action of EGT in reducing phosphorylated NF-κB and JAK/STAT3 expression." (PMID 40046751, 2025). "Here, we demonstrate that in psoriasis, HKGs such as STAT3, PPIF, and EIF5A are co‐opted by the IL‐17/IL‐6 signaling axis to drive keratinocyte activation." (PMID 40959079, 2025). "The prevalence of the rs744166 AA genotype of the STAT3 gene was significantly reduced in the psoriasis cohort compared to the control group." (PMID 40343299, 2025). "CK2 overactivation fosters keratinocyte proliferation and pro-inflammatory cytokine production through the STAT3 and Akt pathways in psoriasis, thus contributing to epidermal hyperplasia and inflammation." (PMID 40508214, 2025). "Experimental data have shown that selective overexpression of STAT3 in KCs in mouse models is sufficient to induce spontaneous psoriasis-like skin changes." (PMID 41226338, 2025). "Other miRNAs, such as miR-21 and miR-146a, are also upregulated in psoriasis and indirectly influence the STAT3 pathway by modulating pro-inflammatory cytokines like IL-6." (PMID 41458345, 2025). "Epidermis models based on Ker-CT_STAT3 responded to IL-22 with stronger expression of the psoriasis marker S100A7, with more pronounced acanthosis and with an increased metabolic activity compared to the wild-type cell line Ker-CT." (PMID 40678130, 2025). "Epidermal keratinocytes in psoriatic lesions are characterized by activated Signal Transducer and Activator of Transcription 3 (STAT3), and transgenic mice with a constitutive activation of Stat3 can develop a phenotype that resembles psoriasis." (PMID 40243580, 2025). "Multiple genetic associations suggest a causative relationship between Th17-related genes coding for proteins, such as IL-17A, IL-23 and STAT3, and psoriasis." (PMID 39820614, 2025). "This pre-psoriatic like phenotype was characterized by higher sensitivity to cytokine treatment and an elevated basal expression of the psoriasis marker S100A7 in STAT3 overexpressing full-thickness skin models." (PMID 40678130, 2025). "The modified LNPs, termed C8B2-si-STAT3, demonstrated superior anti-inflammatory effects compared to conventional LNPs, effectively reducing inflammatory mediators and alleviating psoriasis symptoms in a murine model." (PMID 40724842, 2025).
psoriasis (continued). "In the study, genistein suppressed the expression of inflammatory factors via the downregulation of STAT3 phosphorylation in imiquimod-induced psoriasis skin lesions in mice as well as in TNF-α-stimulated HaCaT cells." (PMID 40429704, 2025). "In summary, the STAT3/NFκB axis is crucial in regulating pyroptosis, with its upregulation contributing to psoriasis pathogenesis and progression." (PMID 40405066, 2025). "Inhibition of STAT3 has been shown in animal studies to be effective for various autoimmune diseases, including psoriasis, rheumatoid arthritis, and inflammatory bowel disease." (PMID 40606688, 2025). "It is inferred that lncRNA-NEAT1 can control the expression of STAT3 by acting as a competitive endogenous RNA (ceRNA) to adsorb miR-485-5p, which is one of the essential mechanisms for the occurrence of psoriasis." (PMID 40110044, 2025). "Another study demonstrated that subcutaneous injection of human umbilical cord MSC exosomes significantly decreased psoriasis-specific cytokines, such as IL-17A and IL-23, and inhibited the phosphorylation of STAT3." (PMID 41007656, 2025). "Hyperactivation of STAT3 in keratinocytes is a characteristic of psoriatic skin which was demonstrated once again in our recently developed in vitro psoriasis model based on STAT3 overexpressing keratinocytes." (PMID 40995100, 2025). "In light of these findings, the NF-κB and JAK/STAT3 pathways are clearly a promising avenue for targeted therapy of psoriasis." (PMID 40046751, 2025). "Compared to the group that was not influenced, the relative expression levels of lncRNA-NEAT1 and STAT3 mRNA are increased in psoriasis tissue, while the miR-485-5p mRNA is reduced." (PMID 40110044, 2025). "Given the known involvement of STAT3 activation and keratinocyte hyperproliferation in psoriasis, we examined the expression of phosphorylated STAT3 (P-STAT3) and K17, a marker of keratinocyte activation, in the epidermis." (PMID 39833165, 2025). "IL-33 exerts immunomodulatory effects by suppressing IL-17A expression in CD4+T cells isolated from psoriasis patients, likely through inhibition of STAT3-dependent IL17A transcription." (PMID 40681996, 2025). "Mice experiments showed that constitutive active STAT3 in keratinocytes induced psoriasis-like lesions and that especially the STAT3 signaling in keratinocytes and not in immune cells is essential for the pathogenesis." (PMID 40678130, 2025). "In the full-thickness skin models STAT3 overexpression by its own was sufficient to induce enhanced expression of the psoriasis marker S100A7." (PMID 40678130, 2025). "Our psoriasis model is highly reproducible as it is based on STAT3 overexpressing immortalized primary keratinocytes." (PMID 40678130, 2025). "We confirmed that the C-terminal eGFP tag did not affect the proteins phosphorylation, as shown by others, making the novel Ker-CT_STAT3 cells well suited for studying STAT3 hyperactivation in psoriasis." (PMID 40678130, 2025). "In skin lesions from patients with psoriasis, levels of phosphorylated signal transducer and activator of transcription 3 (STAT3) were higher than those in normal skin." (PMID 38178928, 2024). "Rutin treatment blocked the JAK2/STAT3 signaling, thus attenuating psoriasis‐related inflammation and anomalous differentiation in keratinocytes." (PMID 39167035, 2024). "The novel topical drug VX-509 also has shown efficacy in diminishing psoriasis inflammation by targeting the STAT3/FABP5 pathway." (PMID 38596682, 2024). "RA inhibits imiquimod-induced psoriasis-like dermatitis in mice by reducing JAK2/Stat3-dependent Th17 cell differentiation and IL-17A production." (PMID 39684446, 2024). "STAT3, a central regulator for Th17 differentiation via IL-23 activation, is overexpressed in psoriasis skin samples, and it constitutes a key regulator for keratinocytes." (PMID 38793117, 2024).
psoriasis (continued). "IL-6 was found to activate the STAT3 and Th17 pathways in psoriasis, promoting inflammation and keratinocyte proliferation." (PMID 39590306, 2024). "Transgenic mice expressing constitutively active STAT3 develop a psoriasis-like phenotype, and STAT3 inhibition prevents skin lesion formation." (PMID 38892253, 2024). "STAT3 and NF-κB p65 are two key transcription factors (TFs) in the pathogenesis of psoriasis, as well as two known downstream TFs of TOPK in cancer." (PMID 39090602, 2024). "The target proteins of these active compounds, including IL1B, TNF, STAT3, IL6, NOS2, and NFKBIA, were found to be directly associated with psoriasis-related disease proteins." (PMID 39590306, 2024). "TOPK modulated the expression of neutrophils chemokines via activating transcription factors STAT3 and NF-κB p65 in keratinocytes, thereby promoting neutrophils infiltration and psoriasis progression." (PMID 39090602, 2024). "The analysis demonstrated that schizandrin II directly influenced psoriasis-related proteins such as IL-4, IL-6, STAT3, and NFKBIA, while schizandrin A modulated the NFKBIA protein." (PMID 39590306, 2024). "HO-1 mediates the suppression of signal transducer and activator of transcription 3 (STAT3), which is critically involved in the pathogenesis and development of psoriasis by promoting inflammation and cell differentiation." (PMID 39590789, 2024). "The expression of JAK1 is positively correlated with the PASI score, and JAK1 and STAT3 tissue expression can be used as markers of psoriasis severity." (PMID 39296901, 2024). "It has demonstrated potential in treating psoriasis by inhibiting the JAK/STAT3 pathway, which counteracts IL-17-induced effects and suppresses VEGF expression." (PMID 38892253, 2024). "Cryptotanshinone can treat psoriasis by inhibiting the activation of STAT3 and reducing the proliferation of keratinocytes in vivo and vitro, thereby alleviating imiquimod-induced epidermal hyperplasia." (PMID 38542838, 2024). "Its inhibition of STAT3 phosphorylation further contributes to its anti-inflammatory effects in psoriatic skin inflammation and offers new strategies for psoriasis treatment." (PMID 38892253, 2024). "The activity of T reg cells is probably impaired in psoriasis, as data sustain that STAT3, activated by pro-inflammatory cytokines, inhibits T reg." (PMID 38793117, 2024). "Provided the central roles of IL-23 and STAT3 in psoriasis pathogenesis, exploring novel mediators within this context is imperative to advance our understanding of disease mechanisms and yield new opportunities for therapeutic development." (PMID 38903528, 2024). "Total glucosides of paeony repressed the phosphorylation of STAT1 and STAT3, thus attenuating animal psoriasis." (PMID 39167035, 2024). "Persistent STAT3 activation, a recognized potential target in psoriasis, is crucial in psoriasis pathogenesis." (PMID 38007430, 2023). "Subsequently, we established an IL-17A treated STAT3 overexpressing mouse model, exhibiting typical pathological psoriasis features such as abnormal proliferation and differentiation of epidermal cells." (PMID 37465147, 2023). "The upregulation of SH3PXD2A-AS1 was found to promote HaCaT cell proliferation and supress HaCaT cell apoptosis, participating in the STAT3/SH3PXD2A-AS1/miR-125b/STAT3 positive feedback loop which affects the pathogenesis of psoriasis." (PMID 38003532, 2023). "Aryl hydrocarbon receptor (AHR)-dependent responses were also evaluated in CD69-deficient mice in a model of psoriasis induced by IL-23, as these mice developed mild psoriasis and showed reduced IL-22 and STAT3 levels." (PMID 37223078, 2023). "STAT1 and STAT3 have recently emerged as key players in the development and pathogenesis of psoriasis." (PMID 36838711, 2023).